LINC-ROR (long independently transcribed non-coding RNA, regulator of reprogramming)
Diseases named in the same sentence as LINC-ROR in open-access papers (continued):
Sharing a sentence is not in itself a finding about the gene and the disease.
triple-negative breast carcinoma (4 papers, 2017 to 2022). An invasive breast carcinoma which is negative for expression of estrogen receptor (ER), progesterone receptor (PR), and human epidermal growth factor receptor 2 (HER2). "Of interest, it is reported that linc-RoR is dramatically overexpressed in triple negative breast cancer (TNBC), and the expression of linc-RoR promotes cell invasion via miR145/ARF6 pathway." (PMID 29041978, 2017). "Furthermore, linc-ROR also acts as a ceRNA of miR-145 and promotes the invasion of triple-negative breast cancer through the linc-ROR/miR-145/ARF6 pathway." (PMID 36139427, 2022).
adenomyosis (3 papers, 2021 to 2025). The growth of endometrial tissue inside the muscular wall of the uterine corpus. "Similarly, upregulation of lncRNA Linc-ROR expression in adenomyosis inhibited PTEN function through phosphorylation." (PMID 40457415, 2025). "Within ectopic endometrial tissue in adenomyosis, LINC-ROR has been proposed to activate the PI3K/Akt signaling pathway, with research indicating that the expression of LINC-ROR and AKT is inversely related to PTEN levels." (PMID 39595579, 2024).
glioblastoma (3 papers, 2021 to 2023). The most malignant astrocytic tumor (WHO grade IV). "Previously, our laboratory showed that lincROR increases the level of a key glioblastoma CSCs marker, CD133, which serves not only as one of the surface markers of CSCs, but is also involved in the pathogenesis of GBM." (PMID 36653583, 2023). "In line with our reports, the heterogeneous expression level of LINC-ROR has been illustrated in glioblastoma, as the up-regulation of LINC-ROR was related to overall survival and poor progression." (PMID 33745265, 2021). "Moreover, the expression of linc-ROR inhibited the proliferation of cancer cells and self-renewal of glioblastoma, partly by inhibiting the KLF4 expression in glioma U87 cell line." (PMID 36827545, 2023). "In this work, we investigated the effect of conditions that reduce the proportion of CSCs in the GBM cell population on the levels of long noncoding RNAs (lincROR and MALAT1) involved in the formation of the phenotype of glioblastoma cancer stem cells." (PMID 36653583, 2023).
lymph node metastasis (3 papers, 2017 to 2023). "In NSCLC the higher linc-ROR expression levels were positively correlated with advanced TNM stage, positive distant metastasis, lymph node metastasis, and poor prognosis." (PMID 36827545, 2023).
oral squamous cell carcinoma (3 papers, 2021 to 2023). "In addition to the gene mutation, we reported Linc-ROR genetic variants which can also play a vital role in the progression of oral squamous cell carcinoma (OSCC), which needs further research studies." (PMID 37903125, 2023). "High levels of Linc-ROR were identified in oral squamous cell carcinomas tissues, often leading to poor treatment response and tumor recurrence." (PMID 34447693, 2021). "Expression of LINC-ROR has been reported to be upregulated in undifferentiated oral squamous cell carcinoma and correlated with the overexpression of KLF4, C-MYC, OCT4, and SOX2." (PMID 33745265, 2021).
osteosarcoma (3 papers, 2017 to 2023). A usually aggressive malignant bone-forming mesenchymal neoplasm, predominantly affecting adolescents and young adults. "In osteosarcoma, linc-ROR was a growth and metastasis promoter via modulating YAP1, the target gene of miR-185-3p, demonstrating its ability to act as a molecular sink for microRNAs." (PMID 36827545, 2023). "Moreover, miR-206 was verified to be a target of linc-ROR in osteosarcoma tissue samples, whereas elevated linc-ROR was closely correlated with advanced tumor–node–metastasis (TNM) stage, lymph node metastasis, and poor overall survival rate." (PMID 36827545, 2023).
pancreatic ductal adenocarcinoma (3 papers, 2016 to 2019). An infiltrating adenocarcinoma that arises from the epithelial cells of the pancreas. "The objective of this study was to analyze linc-ROR expression in pancreatic ductal adenocarcinoma (PDAC) and determine the regulation effects of linc-ROR on proliferation and invasion of cancer cells, as well as properties of cancer stem-like cells (CSLCs)." (PMID 28580169, 2017).
thyroid cancer (3 papers, 2020 to 2024). "In thyroid cancer, CSC-derived exosomes containing lncRNAs such as MALAT1 and linc-ROR, along with transcription factors like SOX2 and SLUG, promote proliferation and induce EMT in normal thyroid cells—specifically when exosomes contain linc-ROR." (PMID 38933820, 2024).
esophageal cancer (2 papers, 2017 to 2020). A primary or metastatic malignant neoplasm involving the esophagus. "We found that linc-ROR repression resulted in the sensitization of EC9706 cells to cisplatin, which is one of the most frequently used chemotherapeutic drug for esophageal cancer." (PMID 29237490, 2017).
non-small cell lung carcinoma (2 papers, 2021 to 2023). A group of at least three distinct histological types of lung cancer, including non-small cell squamous cell carcinoma, adenocarcinoma, and large cell carcinoma. "Another study demonstrated that linc-ROR could enhance the stemness features of EML-ALK+ non-small-cell lung cancer, and the expression of linc-ROR was inhibited because of the increased concentration of crizotinib." (PMID 36827545, 2023).
papillary thyroidal carcinoma (2 papers, 2023). "In a tissue microarray study of papillary thyroid cancer samples, the silencing of linc-ROR increased the expression of miR-145, supporting the role of ROR as an endogenous miR-145 sponge." (PMID 36827545, 2023).
parathyroid neoplasms (2 papers, 2021 to 2023). "Similarly, linc-ROR was significantly downregulated during progression from normal, hyperplastic, and adenomatous parathyroid to parathyroid carcinomas, concluding that linc-ROR may function as a tumor suppressor during parathyroid tumor progression." (PMID 36827545, 2023).
renal carcinoma (2 papers, 2018 to 2023). A carcinoma arising from the epithelium of the renal parenchyma or the renal pelvis. "Comparably, linc-ROR served as a decoy oncoRNA that blocked binding surfaces, preventing the recruitment of histone-modifying enzymes, thereby specifying a new pattern of histone modifications that promote tumorigenesis in renal cancer 293T cells." (PMID 36827545, 2023). "Moreover, a renal cancer study indicated that linc-ROR promotes proliferation and metastasis by binding to miR-206 and promoting VEGF overexpression." (PMID 36827545, 2023).
sarcoma (2 papers, 2020 to 2021). A usually aggressive malignant neoplasm of the soft tissue or bone. "It has been reported that there were a heterogeneous pattern of LINC-ROR expression among Iranian patients in which the esophageal, ovarian, and cervical cancers had over expressions, while there were LINC-ROR down regulations in breast, sarcoma, colon, and melanoma cancer cases." (PMID 31956395, 2020).
bladder tumors (1 paper, 2020). "However, among the sixteen biomarkers, seven of them, namely LINC00355, UCA1-203, HOX-AS-2, Linc-ROR, OCT4, SOX2 and OTX2-AS1, did not demonstrate sufficient discriminatory power to separate bladder tumors from urocystitis, as indicated by their low AUC values (AUC<0.70)." (PMID 31949480, 2020).
embryonic carcinoma (1 paper, 2021). "In addition, underexpression of LINC-ROR has been observed in somatic cancer cell lines, except for undifferentiated ESCs and embryonic carcinoma cell lines." (PMID 33745265, 2021).
gallbladder cancer (1 paper, 2023). "Similarly, the EMT phenotype induced by TGF-β1 was reversed after linc-ROR was knocked out in gallbladder cancer cells, whilst linc-ROR expression level was significantly associated with tumor sizes and lymph node metastasis." (PMID 36827545, 2023).
gastric tumors (1 paper, 2018). "Consistent with our results, we also found overexpression of lncRNAs such as H19, GAS5, TUG1, AP5M1 and MALAT1 and downregulation of LINCROR, POU3F3, HOTAIR, FALEC, NBAT1, and ZEB2-AS1 lncRNAs in TCGA gastric tumor datasets." (PMID 29719612, 2018).
head and neck cancer (1 paper, 2021). A primary or metastatic malignant neoplasm affecting the head and neck. "A previous study presented evidence indicating that FOXM1 could regulate drug resistance in head and neck cancer cells through Linc-ROR." (PMID 34447693, 2021).
ovarian serous cancer (1 paper, 2017). "Our results indicated that linc-ROR is highly expressed in high-grade ovarian serous cancer tissues, and that high linc-ROR expression is associated with advanced FIGO stage and lymph node metastasis." (PMID 29050257, 2017). "We first examined linc-ROR expression in samples of high-grade ovarian serous cancer tissue, normal ovarian tissue, and normal fallopian tube tissue." (PMID 29050257, 2017). "Linc-ROR mRNA was shown to be expressed at higher levels in high-grade ovarian serous cancer tissues than in normal ovarian or normal fallopian tube tissues." (PMID 29050257, 2017). "In conclusion, this study demonstrated that linc-ROR is up-regulated in high-grade ovarian serous cancer tissues, where it promotes proliferation, invasion, and metastasis." (PMID 29050257, 2017). "In this study, we found that linc-ROR expression was increased in high-grade ovarian serous cancer tissues compared with normal ovarian tissues or normal fallopian tube tissues." (PMID 29050257, 2017). "Linc-ROR mRNA expression was assessed by quantitative real-time (qRT)-PCR and shown to be significantly higher in the 39 high-grade ovarian serous cancer tissue samples than in either the 20 normal ovarian tissue samples or the 20 normal fallopian tube tissue samples (P<0.01)." (PMID 29050257, 2017).
tumor (65 papers, 2015 to 2025). "The expression level of LINC-ROR was significantly associated with metastasis to lymph nodes, vascular invasion, and advanced stages of tumor progression, where its expression activated during tumor progression." (PMID 33745265, 2021). "There was an association between the underexpression of LINC-ROR and sex, stage of tumor progression, tumor type, and location of tumor (p < 0.05), and H.pylori infection with SALL4 expression (p = 0.036)." (PMID 33745265, 2021). "Our results indicated that the underexpression of LINC-ROR is associated with tumor type and location, stage of tumor progression, and gender of patients." (PMID 33745265, 2021). "The expression level of linc-ROR was further demonstrated to be closely linked to tumor size and the clinical stage of PC." (PMID 32850817, 2020). "The downregulated linc-ROR expression levels were obviously associated with tumor differentiation, and the high expression linc-ROR group had a better prognosis." (PMID 33163123, 2020). "Intriguingly, the linc-ROR expression levels were obviously associated with tumor differentiation (P = 0.004)." (PMID 33163123, 2020). "For instance, linc‐RoR is found to be overexpressed in undifferentiated tumours and presents closely association with OSCCs tumour recurrence and poor prognosis." (PMID 30394668, 2019). "Considering that Wnt/β-catenin signalling is closely associated with CRC tumor progression and tumorigenesis, we justly wondered whether lincROR mediated the Wnt/β-catenin signalling in CRC tumorigenesis." (PMID 39546475, 2024). "Moreover, linc-ROR overexpression was associated with poorer survival in a CRC study that analyzed 24 tumor tissues and paired normal tissue adjacent to the tumor." (PMID 36827545, 2023). "In addition, studies confirmed that the linc-ROR served as an oncogene in vivo and in vitro and was closely associated with the enlarged tumor volume, advanced TNM stage, shortened OS, and metastasis." (PMID 32850817, 2020). "Linc‐RoR was found to be significantly overexpressed in undifferentiated OSCC samples, and its overexpression was strongly associated with tumor recurrence and poor therapeutic response." (PMID 40256126, 2025). "The results showed that lncRNA RMRP, RPPH1, and linc-ROR were significantly correlated with tumor diameter, lymphatic metastasis, distal metastasis, and TNM stage (all P < 0.05)." (PMID 39925803, 2025). "One of the potential prognostic and predictive biomarkers for NSCLC is the high expression of LINC-ROR which promotes tumor growth and cell proliferation." (PMID 39912974, 2025). "In summary, our findings show that serum EV lncRNA RMRP, RPPH1 and linc-ROR are abnormally expressed in GC and are significantly correlated with tumor size, stage, metastasis, and other clinicopathological factors." (PMID 39925803, 2025). "Overexpression of linc-RoR(Long intergenic non-coding RNA-ROR) in the extracellular tumor environment during hypoxia in HCC cells has been shown to act as a miR sponge for tumor suppressor miR-145, thereby allowing cancer cells to self-renew." (PMID 41186893, 2025). "LincROR was also shown to be involved in the anti-tumour activity of berberine in CRC in our previous research." (PMID 39546475, 2024). "LINC-ROR (Regulator of Reprogramming) is a typical lncRNA that has been involved in supporting stem cell pluripotency as well as tumor progression in earlier research." (PMID 39170516, 2024). "In the present study, we found that knockdown of lincROR significantly inhibited cell viability in vitro, while its overexpression promoted tumor growth in vivo." (PMID 39546475, 2024). "The overexpression of lincROR significantly promoted tumor growth in vivo, as evidenced by the increased tumor volume and weight." (PMID 39546475, 2024). "Although linc-ROR is predominantly documented as an onco-lncRNA, evidence persists in some types of tumors that contradict this function and position linc-ROR as a tumor suppressor." (PMID 36827545, 2023).
tumor (continued). "One of the most studied mechanisms by which linc-ROR promotes cell proliferation and cancer progression is by acting as a sponge for miRNA-145, a micro RNA considered a tumor suppressor in diverse types of cancers." (PMID 36827545, 2023). "According to many studies, the function of linc-ROR as a molecular sink for tumor-suppressor miR-145 promotes EMT and cancer invasiveness capacity." (PMID 36827545, 2023). "Another experiment with sorafenib showed a positive correlation between sorafenib and linc-ROR expression in both tumor cells and extracellular vesicles, exhibiting linc-ROR-dependent effects on tumor-initiating cells and chemoresistance." (PMID 36827545, 2023). "The lncRNA linc-RoR, whose expression was increased in hypoxic regions within tumor cell xenografts in vivo, regulated the hypoxic response through a miR-145/HIF-1α signaling module." (PMID 36127332, 2022). "They found that linc-RoR functioned as a ceRNA for several tumor suppressor miRNAs, particularly some members of the let-7 family." (PMID 35565245, 2022). "linc-ROR is upregulated in tumor tissues and promotes tumor progression by inducing EMT and promoting malignant abilities such as proliferation, migration, etc.." (PMID 36139427, 2022). "Linc-ROR is a tumour promoter, which mainly participates in tumour cell proliferation, apoptosis, invasion, angiogenesis, and cancer stem cell generation by regulating target genes." (PMID 33499813, 2021). "Located on 18q21.31, Linc-ROR has been reported to contribute to tumor growth by means of regulating the reprogramming of plu ripotent stem cells." (PMID 34447693, 2021). "The co-expression of LINC-ROR and SALL4 was significantly associated with the depth of tumor invasion (T2; p = 0.002) and tumor grade of II (p = 0.05)." (PMID 33745265, 2021). "TGF-β enriched linc-RoR within exosomes, resulting in suppression of chemotherapy-induced cell death and tumor-initiating cell proliferation." (PMID 32503591, 2020). "This review summarizes the status of linc-ROR research in various human cancers and discusses its mechanism and clinical significance in the development and progression of tumor." (PMID 32850817, 2020). "For example, linc-ROR was found abundant in tumor cells as well as in exosomes derived from tumor cells." (PMID 32370770, 2020). "Secondly, the expression of linc-ROR needs to be detected in blood samples to be more suitable for a tumor biomarker." (PMID 33163123, 2020). "In summary, our results demonstrated that Curcumin plays an anti-tumor function through the linc-ROR/β-catenin regulatory pattern in HCC." (PMID 32714183, 2020). "Tumor suppressive lncRNAs (GAS5, MEG3, FER1L4 and LINC00672) and oncogenic lncRNAs (CCAT2, BANCR, NEAT1, MALAT1, H19 and Linc-RoR) have been identified as key regulators of the established tumor suppressor or oncogenic pathways in EC." (PMID 30781521, 2019). "LncRNA regulator of reprogramming (linc-ROR) had a higher expression in NCSLC tissues than adjacent non-tumor tissues, and this elevated linc-ROR expression positively correlated to advanced TNM stage and lower five-year overall survival." (PMID 31889958, 2019). "High levels of linc-RoR were detected in tissue samples from tumor relapse and drug-resistant patients, suggesting that clinical detection of linc-RoR level predicted the prognosis and therapeutic effects of OSCC." (PMID 31133028, 2019). "Our results confirm the upregulation of linc-ROR in tumour tissue of CRC patients across all stages." (PMID 30205577, 2018). "Overexpression of linc-ROR seems to be responsible for promoting proliferation and invasion of cancer cells as well as tumor growth in nude mice." (PMID 30250400, 2018). "We first divided the 94 patients into two groups, the low- and high-expression groups, according to the linc-ROR levels in the tumor tissues." (PMID 30250400, 2018).